TENT5C (terminal nucleotidyltransferase 5C)
Description:
Catalyzes the transfer of one adenosine molecule from an ATP to an mRNA poly(A) tail bearing a 3'-OH terminal group and enhances mRNA stability and gene expression. Can also elongate RNA oligos ending with uridine molecule, provided that the sequence is adenosine-rich. Mainly targets mRNAs encoding endoplasmic reticulum-targeted protein. (Microbial infection) Seems to enhance replication of some viruses, including yellow fever virus, in response to type I interferon.
Synonyms: FAM46C; FLJ20202
Tractability: PROTAC: ubiquitination databases record sites on it.
Gene: Protein-coding gene on chromosome 1 (117,606,048 to 117,628,389, forward strand). Ensembl gene ENSG00000183508.
Subcellular location: Nucleus; Cytoplasm; Cytoplasm, cytoskeleton, microtubule organizing center, centrosome
Subcellular location (Human Protein Atlas): Nucleoplasm
Gene Ontology:
Molecular function: poly(A) RNA polymerase activity; protein binding
Biological process: mRNA stabilization; negative regulation of cell differentiation
Cellular component: centrosome; cytoplasm; nucleoplasm; nucleus
Genetic constraint (gnomAD): Loss-of-function variants: 5 observed, 23.46 expected, observed/expected ratio (o/e) 0.21, 90% interval 0.11 to 0.45. The upper end of that interval is the gene's LOEUF score, 0.45, which puts it in group 1 of 6, group 1 being the genes least tolerant of losing a copy. Missense variants: 364 observed, 526.46 expected, observed/expected ratio (o/e) 0.69, 90% interval 0.63 to 0.75. Synonymous variants: 199 observed, 205.78 expected, observed/expected ratio (o/e) 0.97, 90% interval 0.86 to 1.09.
Cancer hallmarks: suppression of growth (promotes); genome instability and mutations (suppresses); escaping programmed cell death (suppresses); invasion and metastasis (suppresses); change of cellular energetics
Homologues: Orthologues: chimpanzee TENT5C (99% identical), macaque TENT5C (99% identical), dog TENT5C (97% identical), guinea pig TENT5C (96% identical), rat Tent5c (96% identical), mouse Tent5c (96% identical), pig TENT5C (95% identical), tropical clawed frog tent5c (83% identical), zebrafish tent5c (75% identical), Drosophila melanogaster CG46385 (59% identical), Caenorhabditis elegans tent-5 (43% identical), Caenorhabditis elegans T23F11.6 (14% identical), and 4 more. Paralogues in human: TENT5A (72% identical), TENT5B (63% identical), TENT5D (57% identical).
Diseases named in the same sentence as TENT5C in open-access papers:
TENT5C is named in the same sentence as 47 diseases in open-access papers, as found by Europe PMC text mining. Sharing a sentence is not in itself a finding about the gene and the disease. The quoted sentences say what the papers report.
multiple myeloma (22 papers, 2014 to 2025). "TENT5C has been proposed to mediate the susceptibility of multiple myeloma to treatment with dexamethasone, a steroid hormone analog that binds to the glucocorticoid receptor (GR)." (PMID 40421654, 2025).
hepatocellular carcinoma (10 papers, 2017 to 2024). A malignant tumor that arises from hepatocytes. "TENT5C expression is significantly lower in hepatocellular carcinoma (HCC) than in normal liver tissue." (PMID 33145994, 2021).
leukaemia (2 papers, 2022 to 2026). "Furthermore, our results also suggest that in leukemia cells, TENT4A, TENT5A, TENT5B, TENT5C, TENT5D, and TUT1 may mediate the non-templated nucleotide additions to the 3'ends of miRNAs." (PMID 42038404, 2026).
viral infection (2 papers, 2023). "For the genes with cis-regulatory DRE in viral infections, Ctps and Tent5c served as the critical signal factors in lymphocyte proliferation and Kmt2d regulates CD8 T cell development and differentiation." (PMID 37081881, 2023).
Infertility (1 paper, 2024). "A model that provided us with additional insight into the role of TENT5B and TENT5C in oocyte biology was a mouse knock-in line expressing TENT5B with a C-terminal GFP tag (TENT5B-GFP), which, as previously stated, displayed specific infertility in females." (PMID 38909026, 2024).
melanoma (1 paper, 2024). A malignant, usually aggressive tumor composed of atypical, neoplastic melanocytes. "For example, TENT5C was identified as a tumor suppressor, exerting its function by inhibiting Plk4 activity in melanoma." (PMID 38502270, 2024).
tumor (17 papers, 2017 to 2026). "Apart from immune system related genes we also find a number of genes involved in tumor suppression including Tes and Tent5c." (PMID 37575232, 2023). "A significant top-scoring model (tumour stage, age, CIITA, IKZF3, CD247, TENT5C; likelihood ratio test p = 2 × 10−7) was returned for the MEL_TCGA training set (n = 255, TCGA_TRAIN)." (PMID 35743743, 2022).
cancer (9 papers, 2020 to 2025). A tumor composed of atypical neoplastic, often pleomorphic cells that invade other tissues. "Terminal nucleotidyltransferase 5C (TENT5C) is a noncanonical poly(A) polymerase that promotes cancer suppression." (PMID 40421654, 2025).
TENT5C also shares sentences with these, for which no sentence is quoted: gastric cancer (4 papers); colorectal cancer (2); lung carcinoma (2); periodontitis (2); prostate carcinoma (2); acute myeloid leukaemia (1); B-cell lymphoma (1); breast adenocarcinoma (1); breast invasive carcinoma (1); Cerebral ischemia (1); cervical squamous cell carcinoma (1); colon adenocarcinoma (1); colorectal adenocarcinoma (1); COVID-19 (1); glioblastoma (1); head and neck squamous cell carcinoma (1); Huntington disease (1); kidney cancer (1); liver cancer (1); lymphoma (1); multiple sclerosis (1); non-small cell lung carcinoma (1); oesophageal cancer (1); ovarian carcinoma (1); pancreatic adenocarcinoma (1); pancreatic cancers (1); pancreatic ductal adenocarcinoma (1); paraganglioma (1); pheochromocytoma and (1); promyelocytic leukemia (1).
A further 9 diseases each share a sentence with TENT5C in 1 paper.